PDSS1 (decaprenyl diphosphate synthase subunit 1)
Description:
Heterotetrameric enzyme that catalyzes the condensation of farnesyl diphosphate (FPP), which acts as a primer, and isopentenyl diphosphate (IPP) to produce prenyl diphosphates of varying chain lengths and participates in the determination of the side chain of ubiquinone. Supplies nona and decaprenyl diphosphate, the precursors for the side chain of the isoprenoid quinones ubiquinone-9 (Q9)and ubiquinone-10 (Q10) respectively. The enzyme adds isopentenyl diphosphate molecules sequentially to farnesyl diphosphate with trans stereochemistry.
Synonyms: TPT 1; TPRT; TPT; COQ1; COQ1A; COQ10D2; DPS; SPS; hDPS1
Tractability: PROTAC: ubiquitination databases record sites on it.
Gene: Protein-coding gene on chromosome 10 (26,697,669 to 26,746,798, forward strand). Ensembl gene ENSG00000148459.
Subcellular location: Mitochondrion
Subcellular location (Human Protein Atlas): Cytosol
Pathways (Reactome):
Metabolism: Ubiquinol biosynthesis
Gene Ontology:
Molecular function: all-trans-decaprenyl-diphosphate synthase activity; protein binding; all-trans-nonaprenyl-diphosphate synthase (geranyl-diphosphate specific) activity; prenyltransferase activity
Biological process: isoprenoid biosynthetic process; ubiquinone biosynthetic process
Cellular component: heterotetrameric polyprenyl diphosphate synthase complex; mitochondrion; mitochondrial matrix; polyprenyl diphosphate synthase complex; protein-containing complex
Genetic constraint (gnomAD): Loss-of-function variants: 22 observed, 27.02 expected, observed/expected ratio (o/e) 0.81, 90% interval 0.58 to 1.16. The upper end of that interval is the gene's LOEUF score, 1.16, which puts it in group 5 of 6, group 1 being the genes least tolerant of losing a copy. Missense variants: 284 observed, 344.71 expected, observed/expected ratio (o/e) 0.82, 90% interval 0.75 to 0.91. Synonymous variants: 130 observed, 132.54 expected, observed/expected ratio (o/e) 0.98, 90% interval 0.85 to 1.13.
Gene-disease validity (ClinGen):
ClinGen rates the evidence that PDSS1 causes each of these diseases.
mitochondrial disease (autosomal recessive): Moderate.
Homologues: Orthologues: chimpanzee PDSS1 (99% identical), macaque PDSS1 (97% identical), dog PDSS1 (89% identical), pig PDSS1 (87% identical), guinea pig PDSS1 (87% identical), rat Pdss1 (84% identical), mouse Pdss1 (84% identical), rabbit PDSS1 (83% identical), tropical clawed frog pdss1 (67% identical), zebrafish pdss1 (61% identical), Drosophila melanogaster qless (47% identical), Caenorhabditis elegans coq-1 (38% identical). Paralogues in human: PDSS2 (24% identical), GGPS1 (15% identical).
Diseases named in the same sentence as PDSS1 in open-access papers:
PDSS1 is named in the same sentence as 57 diseases in open-access papers, as found by Europe PMC text mining. Sharing a sentence is not in itself a finding about the gene and the disease. The quoted sentences say what the papers report.
hepatocellular carcinoma (6 papers, 2020 to 2024). A malignant tumor that arises from hepatocytes. "To explore the impact of PDSS1 on HCC, we applied WB to detect the PDSS1 expression pattern in human hepatocellular carcinoma cell lines (HepG2, LM3, Huh7, Hep3B, and SMMC-7721)." (PMID 35965499, 2022). "Studies have predicted that PDSS1 is associated with hypoxia and immune microenvironment in hepatocellular carcinoma, but the molecular mechanism by which it acts has not been reported." (PMID 35965499, 2022). "In hepatocellular carcinoma (HCC), a novel prognostic signature composed of 6 key lactate metabolism-related genes (FKTN, PDSS1, PET117, PUS1, RARS1, and RNASEH1) was developed to predict the survival and tumor microenvironment of HCC patients." (PMID 38529390, 2024). "The results showed that PDSS1, SLC7A11 and CDCA8 were significantly upregulated in hepatoma cell lines (P < 0.05)." (PMID 32887635, 2020). "In hepatocellular carcinoma (HCC), transcriptomic data revealed a lactate metabolism-related gene signature (LMRGS) based on the expression of six genes (FKTN, PDSS1, PET117, PS1, RARS1, and RNASEH1)." (PMID 36713558, 2022).
optic atrophy (5 papers, 2020 to 2025). A disorder characterized by loss of optic nerve fibers. "Individuals with disease-causing variants in PDSS1 typically present with deafness, optic atrophy and muscular hypotonia (primary coenzyme Q10 deficiency-2; COQ10D2; OMIM #614651)." (PMID 36978966, 2023). "Furthermore, very few reports suggest a strong association between mutations in PDSS1 and optic atrophy or sensorineural deafness." (PMID 38054206, 2023). "It is interesting to note that some patients with inherited pathogenic variants in genes implicated in primary CoQ10 deficiency manifest with optic atrophy as a feature of complex neurological phenotypes, including mutation of COQ1/PDSS1, COQ2 and COQ6." (PMID 40859035, 2025). "Other genes in the biosynthetic pathway have been associated with other ocular abnormalities other than pigmentary retinopathy, such as such as optic atrophy (e.g., PDSS1/2)." (PMID 33187544, 2020).
breast carcinoma (3 papers, 2019 to 2022). "The exact biological role of PDSS1 is unclear, but the expression of PDSS1 has been associated with the breast cancer response to the first-generation SERM, tamoxifen." (PMID 35456610, 2022). "In addition, previous literature has shown that PDSS1 promotes breast cancer progression through the STAT3 signaling pathway." (PMID 35965499, 2022).
coenzyme Q10 deficiency (2 papers, 2011 to 2021). A genetically heterogeneous condition, typically inherited in an autosomal recessive fashion, characterized by coenzyme Q10 deficiency. "This is the first reported patient with PDSS1 mutations presenting with 3‐methyl‐glutaconic aciduria and distal phalangeal erythema, expanding the phenotype of primary coenzyme Q10 deficiency." (PMID 34765390, 2021). "In conclusion, our data expand the phenotypic spectrum associated with PDSS1 variants and primary coenzyme Q10 deficiency." (PMID 34765390, 2021). "A germ-line mutation in PDSS1 was identified in two siblings with cardiac disease and mental retardation associated with coenzyme Q10 deficiency." (PMID 21291537, 2011).
kidney failure (2 papers, 2023 to 2025). An acute or chronic condition that is characterized by the inability of the kidneys to adequately filter the blood. "In conclusion, we report a young patient with a neurodevelopmental phenotype of PDSS1-related primary CoQ10 deficiency, who also developed SRNS that progressed to kidney failure and necessitated hemodialysis." (PMID 39656276, 2025).
liver cancer (2 papers, 2022). An epithelial or non-epithelial malignant neoplasm that arises from the liver. "Moreover, based on the TCGA database, we divided liver cancer patients into high and low groups according to their PDSS1 expression levels, and analyzed the relationship between PDSS1 and clinicopathological characteristics." (PMID 35965499, 2022).
Nephropathy (2 papers, 2021 to 2025). A nonspecific term referring to disease or damage of the kidneys. "Both our patient and the previously reported case demonstrated rapid progression of renal disease, ultimately resulting in death, suggesting that PDSS1 mutations may be linked to a more severe clinical presentation." (PMID 39656276, 2025).
pancreatic cancer (2 papers, 2017 to 2022). "In particular, we observed normalization of expression of KRAS, which is directly related to pancreatic cancer progression, and mevalonate pathway related genes (HMGCS1, MVD, MVK, and PDSS1)." (PMID 29262834, 2017).
Sepsis (2 papers, 2025). Sepsis is defined as life-threatening organ dysfunction caused by a dysregulated host response to infection. "qRT-PCR validation demonstrated significantly elevated expression of TGFA (P = .0306), GNAQ (P = .0185), and PDSS1 (P = .0052) in septicemia patients." (PMID 41305715, 2025). "Our study found that PDSS1 is significantly over-expressed in neonates with sepsis." (PMID 41424725, 2025).
triple-negative breast carcinoma (2 papers, 2022). An invasive breast carcinoma which is negative for expression of estrogen receptor (ER), progesterone receptor (PR), and human epidermal growth factor receptor 2 (HER2). "A recent study reported upregulated PDSS1 expression and PDSS1 protein levels in triple-negative breast cancer tissues." (PMID 35204836, 2022).
Alzheimer disease (1 paper, 2025). A progressive, neurodegenerative disease characterized by loss of function and death of nerve cells in several areas of the brain leading to loss of cognitive function such as memory and language. "Lysosome, alzheimers disease and oxidative phosphorylation were pathways enriched for PDSS1." (PMID 41305715, 2025).
cerebellar ataxia (1 paper, 2017). A neurological syndrome characterized by clumsy and uncoordinated movement of the limbs, trunk, and cranial muscles. "It should be also emphasised that rare autosomal recessive disorder, CoQ10 deficiency (mutation in CABC1; COQ2; COQ9; PDSS1; PDSS2 genes), is frequently associated with seizures, cognitive decline, pyramidal track signs, myopathy, and prominent cerebellar ataxia." (PMID 29456787, 2017).
developmental delays (1 paper, 2025). "Patients with reported PDSS1 mutations typically present with developmental delays and neurological symptoms." (PMID 39656276, 2025).
glomerular disease (1 paper, 2022). "Mutations in genes related to coenzyme Q10, another mitochondrially associated antioxidant, including PDSS1, PDSS2, COQ2, COQ6, and COQ8B/ADCK4, are associated with the development of glomerular disease." (PMID 34874915, 2022).
Leukoencephalopathy (1 paper, 2023). This term describes abnormality of the white matter of the cerebrum resulting from damage to the myelin sheaths of nerve cells. "Another brain pathology observed in individuals with COQ defects is disturbed myelination and leukoencephalopathy (PDSS1, COQ2, COQ6, COQ7 and HPDL)." (PMID 36978966, 2023).
postmenopausal osteoporosis (1 paper, 2025). Metabolic disorder associated with fractures of the femoral neck, vertebrae, and distal forearm. "Moreover, polymorphisms in estrogen metabolism-related genes, such as PDSS1, CYP19A1, CYP1A1, and CYP1B1, have been associated with varied efficacy of raloxifene, a selective estrogen receptor modulator frequently prescribed for postmenopausal osteoporosis." (PMID 40411668, 2025).
retinal dystrophies (1 paper, 2025). "Indeed, 14 genes that are differentially bound by PRPF8Y2334N in RPE cells have been associated with various retinal dystrophies and four genes (MVK, PDSS1, MERTK and SEMA4A) are involved in RP." (PMID 40045025, 2025).
retinitis pigmentosa (1 paper, 2025). Retinitis pigmentosa (RP) is an inherited retinal dystrophy leading to progressive loss of the photoreceptors and retinal pigment epithelium and resulting in blindness usually after several decades. "Oxidative stress caused downregulation of Pdss1 and Abcc6, known to be involved in retinitis pigmentosa and retinopathy." (PMID 41326361, 2025).
tumor (5 papers, 2015 to 2024). "Our findings not only elucidate prognostic value of PDSS1 in HCC but also deepen our understanding of the tumor microenvironment and the metabolic dependencies of cancer cells." (PMID 39132167, 2024). "Using the scMetabolism package, we found that almost all metabolites are enriched in epithelial cells with high PDSS1 expression, suggesting that PDSS1 constructed a high metabolic tumor microenvironment, thereby affecting other cells." (PMID 39132167, 2024). "Epithelial cells with high PDSS1 expression mainly appear in the middle stages of tumor development." (PMID 39132167, 2024). "The results confirmed that in epithelial cells with high PDSS1 expression, the regulatory activity of TFs related to tumor progression was significantly enhanced." (PMID 39132167, 2024). "Through CellChat analysis, we found that epithelial cells with high PDSS1 expression in both tumor tissues and normal tissues had stronger cell communication with surrounding cells." (PMID 39132167, 2024). "In our study, the application of scRNA-seq has profoundly characterized tumor cells with high PDSS1 expression, revealing unique transcriptional and metabolic features, as well as interactions with the immune microenvironment." (PMID 39132167, 2024). "This work not only elucidated the role of PDSS1 in HCC but also enhanced our understanding of cuproptosis dynamics during tumor progression." (PMID 39132167, 2024). "To explore the role of PDSS1 in the tumor immune microenvironment, we used immune infiltration analysis to analyze the infiltration of different immune cells following changes in the expression level of PDSS1." (PMID 35965499, 2022). "Furthermore, we detailed the characteristics of high PDSS1-expressing tumor cells, including their distinctive transcription factors, metabolic profiles, and interactions with different subtypes within the tumor microenvironment." (PMID 39132167, 2024). "This indicates that PDSS1 may affect the occurrence and development of tumors by changing these biological metabolic processes and provides new insights for the study of tumor metabolism." (PMID 35965499, 2022). "To explore the prospects of PDSS1 in tumor drug treatment, we predicted PDSS1-related cancer pathways and the drug sensitivity of PDSS1.The results indicated that PDSS1 is probably involved in the activation of the cell cycle, DNA damage response, apoptosis, and hormone AR pathways." (PMID 35965499, 2022). "On the other hand, PDSS1 is significantly positively correlated with Th2 cells, TFH, and T helper cells, and they play an important role in regulating tumor immunity." (PMID 35965499, 2022). "Among the genes significantly co-activated in G3 basal-like tumor samples, we identified 3 reproducible and concordantly up-regulated SAGPs (ABI1/PDSS1, DIS3/BORA and WDR77/ATP5F1)." (PMID 26517092, 2015). "Moreover, by analyzing gene expression in GSE6764 cohort, we found that the expression levels of PDSS1, CDCA8 and SLC7A11 were significantly higher in tumor tissue than those in liver nodules." (PMID 32887635, 2020).
cancer (4 papers, 2020 to 2024). A tumor composed of atypical neoplastic, often pleomorphic cells that invade other tissues. "Based on the data from the TCGA and GTEx databases, we first evaluated PDSS1 expression in pan-cancers using GEPIA." (PMID 35965499, 2022). "PDSS1 is involved in coenzyme Q biosynthesis, but little is known about the relationship between PDSSI and cancer." (PMID 32887635, 2020).
mitochondrial disease (3 papers, 2019 to 2025). "PDSS1 mutations hamper Coenzyme Q10 biosynthesis and cause a rare multisystem mitochondrial disease characterized by diverse clinical features and limited treatment options." (PMID 39656276, 2025).
PDSS1 also shares sentences with these, for which no sentence is quoted: nephrotic syndrome (3 papers); deafness (2); axonal neuropathy (1); bladder urothelial carcinoma (1); breast infiltrating carcinoma (1); cardiac disease (1); cervical cancer (1); cognitive decline (1); encephalomyopathy (1); esophageal carcinoma (1); gastric cancer (1); glioblastoma (1); glycogen storage diseases (1); infection (1); lactic acidosis (1); Leigh syndrome (1); leprosy (1); leukemia (1); Livedo reticularis (1); lung adenocarcinoma (1); lung squamous cell carcinoma (1); mental retardation (1); Mitochondrial encephalopathy (1); myopathy (1); neuromuscular disease (1); Obesity (1); ovarian carcinoma (1); Pigmentary retinopathy (1); primary coenzyme Q10 deficiency-2 (1); pulmonary hypertension (1).
A further 6 diseases each share a sentence with PDSS1 in 1 paper.